TAAR1 (trace amine associated receptor 1)
Diseases named in the same sentence as TAAR1 in open-access papers (continued):
Sharing a sentence is not in itself a finding about the gene and the disease.
cancer (continued). "RNAseq data from 12 published cancer studies obtained from cBioPortal detected RNA for TAAR1, TAAR2, TAAR5, TAAR6, TAAR8, and TAAR9 in various cancers." (PMID 29997511, 2018). "TAAR1 and TAAR9 were also detected in cancer-associated fibroblasts (CAF)." (PMID 35053262, 2022). "Recently, the role of TAAR1 in different cancers has become a topic of emerging interest." (PMID 33113952, 2020). "TAAR1 signaling may modulate tumor cell function to alter malignancy and tumor progression and therefore TAAR1-specific compounds could potentially have oncological therapeutic potential and represent a novel approach to modulating cancer physiology." (PMID 29997511, 2018). "We discuss connections and logical directions for further study of TAAR1 in immunological function, and its potential role as a mediator or modulator of immune dysregulation, immunological effects of psychostimulant drugs of abuse, and cancer progression." (PMID 29997511, 2018). "Accordingly, our analyses of TAAR1 expression trends in overall survival cancer studies raises speculation of TAAR1 as a possible prognostic marker." (PMID 29997511, 2018). "Here, we review the immunologically relevant TAAR1 literature and incorporate open-source expression and cancer survival data as a mode of observational insight into physiologically-relevant topics of interest not only to the TAAR1 research community, but also to other life science investigators." (PMID 29997511, 2018). "TAAR1 signaling may play a role in the progression of many cancers, and accordingly TAAR1-specific compounds may serve as potential therapeutic additions to current clinical practices to improve survival." (PMID 29997511, 2018). "We estimated TAARs’ (including TAAR1, TAAR2, TAAR5, TAAR6, TAAR8, and TAAR9) associations with BC stage, grade, and molecular subtypes in these data and identified that the expression of all TAARs was associated with more unfavorable cancer subtypes, including basal-like and HER2-positive tumors." (PMID 37759760, 2023). "The tryptamine receptor TAAR1 is a potential cancer prognosis biomarker and it could induce the transcription of the aryl hydrocarbon receptor (AHR) target gene cytochrome P450 1A1 (CYP1A1), leading to the activation of the conversion of organic compounds to cytotoxic or carcinogenic species." (PMID 36232383, 2022). "Although the differential pattern of TAAR1 expression in diverse cancers would suggest that the role of this receptor might be different depending on the cancer type, the limited number of functional studies performed so far point to the activation of TAAR1 as a possible anti-neoplastic strategy." (PMID 33113952, 2020). "Therefore, the available evidences at present suggest that TAAR1 might represent a relevant pharmacological target against some cancers, which makes essential the development of specific TAAR1 agonists." (PMID 33113952, 2020). "Notably, SPP-1 upregulation is inducible by PKC activation, a signaling pathway triggered by TAAR1 agonists, and its expression is inversely related to cancer prognosis as tumors rich in the SPP-1 gene have an enhanced ability to grow and invade other tissues to ultimately metastasize." (PMID 29997511, 2018). "We provide strong evidence for TAAR1 expression in the immune system and cancers revealed through NCBI GEO datamining and discuss its regulation in a spectrum of immune cell types as well as in numerous cancers." (PMID 29997511, 2018). "Interestingly, cancer types containing a majority of samples without detectable TAAR1 expression also contained a number of samples with vastly varied expression levels, suggesting that TAAR1 expression varies in a patient-dependent manner even within a given cancer type." (PMID 29997511, 2018).
neurological disorders (6 papers, 2016 to 2024). "The recent discovery of the mammalian G-protein-coupled receptor with high affinity for tyramine, TAAR1, and the implications of TAAR1 in neurological disorders highlight the potential importance of tyraminergic signaling in vertebrate nervous systems." (PMID 30065850, 2018). "The trace amine associated receptor 1 (TAAR1) is a G-protein coupled receptor expressed in the monoaminergic regions of the brain, and represents a potential novel therapeutic target for the treatment of neurological disorders." (PMID 30233365, 2018). "Implications of TAAR1 in major neurological diseases and psychopathological disorders." (PMID 27092049, 2016). "The novel findings discussed in this review uncover the pivotal role of TAs and their associated receptors in the functional regulation of classical aminergic systems and highlight the relevance of TAAR1 as a molecular target to engineer innovative forms of treatment for neurological disease." (PMID 27092049, 2016).
tumor (6 papers, 2018 to 2026). "The co-expression of these receptors in tumors supports the possibility of modulating epinephrine and 5-HT signals in tumor tissue by TAAR1." (PMID 37759760, 2023). "The identified differences in TAAR2 and TAAR5 expression levels between tumor cells and stroma seem to be reproducible in different groups, including inflammatory cancer, whilst tumorous and stromal cells demonstrate similar expression levels of TAAR1, TAAR6, and TAAR8." (PMID 37759760, 2023). "The overlap between genes co-expressed with TAARs in primary tumors and metastatic lesions is significant, and we found correlations between the expression levels of TAAR1, TAAR2, TAAR5, TAAR8, and TAAR9 and genes associated with neuroactive ligand signaling in both kinds of neoplasms." (PMID 37759760, 2023). "Other TAARs, i.e., TAAR1, TAAR6, and TAAR9, are expressed in the neoplastic epithelium and tumor stroma at the same levels." (PMID 37759760, 2023). "However, the role of TAAR1 in this effect remains unknown, since T1AM is internalized in tumor cells and co-localized with mitochondria." (PMID 37759760, 2023).
infection (2 papers, 2016 to 2018). The state of being infected such as from the introduction of a foreign agent such as serum, vaccine, antigenic substance or organism. "To explore changes in transcript levels of TAAR1 and related TAARs over the course of infection we obtained the raw count data for all samples and calculated log2 fold-change values for each infection stage relative to control tissues." (PMID 29997511, 2018). "Additionally TAAR1 is expressed on lymphocytes and astrocytes involved in inflammation and response to infection." (PMID 27031617, 2016).
bacterial infection (1 paper, 2024). "The joint activation of TAAR1 and TAAR2 stimulates neutrophil migration, which could indicate an important role of these receptors in the primary immune response, for example, in response to bacterial infection." (PMID 38672247, 2024).
central nervous system disorder (1 paper, 2024). A disease involving the central nervous system. "Three main results emerged from our virtual screens based on computational models of TAAR1, a promising therapeutic target for central nervous system disorders." (PMID 39110804, 2024).
TAAR1 also shares sentences with these, for which no sentence is quoted: substance abuse (4 papers); anxiety disorder (3); mood disorder (3); attention deficit-hyperactivity disorder (2); Cataplexy (2); generalized anxiety disorder (2); Impaired glucose tolerance (2); uterine cancer (2); alcohol addiction (1); autoimmune disease (1); brain diseases (1); chronic hepatitis B (1); cryptococcosis (1); diabetic cardiomyopathy (1); Diarrhea (1); endometrioid tumor (1); esophageal cancer (1); Familial adenomatous polyposis (1); functional dyspepsia (1); Gastrointestinal Disorders (1); headache disorder (1); Huntington disease (1); Hyperglycemia (1); hyperprolactinemia (1); Hypoglycemia (1); Hypothermia (1); infectious disease (1); Infertility (1); ischemia (1); juvenile idiopathic arthritis (1).
A further 23 diseases each share a sentence with TAAR1 in 1 paper.